IFNG (interferon gamma)
Diseases named in the same sentence as IFNG in open-access papers (continued):
Sharing a sentence is not in itself a finding about the gene and the disease.
infection (continued). "Strikingly, a significant increase in IFNγ gene expression was measured in gastric tissue from mice vaccinated with WC H. pylori antigen and α-GalCer compared with the infection control group, whereas no significant increase in IL-17A gene expression was observed 3 weeks post infection." (PMID 31666991, 2019). "Production of the cytokine IFNγ by CD8+ T cells has been correlated with less severe cardiac disease; therefore, a therapeutic vaccine which bolsters the TH1-mediated CD8+ T cell immune response to the infection, might slow or halt the progression of disease." (PMID 31145733, 2019). "Analysis of CD4+ T cell subsets revealed an increase in TFH cells and IFNγ-, IFNγ+ TNF+-, and IL-2-producing CD4+ T cells and a decrease in Treg cells in Mock-immune compared with ZIKV-immune mice, which is consistent with the observation that Treg cell number peaks at day 3 after primary infection." (PMID 30677097, 2019). "We demonstrate that while the endogenous NP311-specific CD4 T cell response is largely IFNγ-focused, with cells presumably belonging to the Th1 subset, NP311-specific CD4 T cells represent only a small fraction of the total antigen-experienced CD4 T cells in the lungs following infection." (PMID 31632414, 2019). "Although WT mice vaccinated with antigen and α-GalCer showed a significant reduction of bacteria in the stomach compared with unimmunised mice (infection control group), in the IFNγ−/− mice no significant reduction in bacterial levels could be seen." (PMID 31666991, 2019). "Indeed, in seronegative individuals, they have shown transient activation of a subset of IFNγ-secreting CD16brightCD56dim NK cells known to rapidly respond to infection without prior sensitization." (PMID 32038634, 2019). "Previous in vitro studies suggested that Cryptosporidium might interfere with IFNγ induced expression of the major histocompatibility complex (MHC), but infection of mice led to global upregulation of epithelial cell MHC class I and II expression (data not shown)." (PMID 31231045, 2019). "Under non-infection conditions, B. pilosa did not boost IFNγ production." (PMID 30814608, 2019). "We have shown that peptides from these proteins are also recognized by IFNγ secreting cells by lymphocytes from ASFV-immune pigs, and have identified a further 36 ORFs from which pools of peptides stimulate IFNγ-producing cells primed by infection with the OUR T88/3 strain of the virus." (PMID 31275307, 2019). "However, in our experiments, IFNγ- activated granuloma macrophages treated with AhR ligands did not exhibit changes in NO secretion upon infection with L. major." (PMID 31749794, 2019). "In contrast to the clear MyD88-dependence of these chemokines and IFNγ-response genes, the induction of the immunoregulatory cytokine IL-10 and of the enzyme Arginase-1 by NMII was largely independent of MyD88, which contrasts to the results obtained with BMM after infection with NMII in vitro." (PMID 30800124, 2019). "Intriguingly, IFNG inhibits the replication of MNV in an Atg5-dependent manner at the formation step of the MNV replication compartment (RC), which are structures formed during infection with multiple positive-sense RNA viruses, and where viral genome replication takes place." (PMID 30871000, 2019). "Therefore, the effects of IFNγ on bystander cells creates an environment that is not conducive to the development of secondary infections, thereby limiting spread of a primary infection." (PMID 29855501, 2018). "Also, we emphasize that ROS affect T. cruzi growth inside only unstimulated macrophages and thus are more likely to be relevant at the very beginning of infection, when the production of IFNγ is still low and most macrophages are not activated to produce NO." (PMID 29672619, 2018).
infection (continued). "However, more recently IL-27 has also been shown to act as a negative regulator of ongoing immune responses during infection and autoimmune inflammation and under these circumstances IL-27 can limit pro-inflammatory cytokine production by CD4 T cells, including IFNγ." (PMID 30044874, 2018). "Furthermore, mice that received HSV-2 + Cc-BmKn2 or HSV-2 + Cc-Control had no increase in IFNγ in the vaginal tract at 24 hours post-infection." (PMID 29434285, 2018). "Thus, we speculate that, in the setting of infection or other IPP-inducing cellular stresses such as cancer, CL-induced activation of IL-4-producing γδ T cells in SSc, together with a decrease of IFNγ-producing γδ T cells, may contribute to organ fibrosis." (PMID 29706966, 2018). "Against this, we observe an expansion of Ag85-specific CD4+ T cells with infection, alterations on the T cell activation profile that are more exuberant in the transgenic over the non-transgenic cells and more IFNγ+ and TNF+ CD4+ T cells in the transgenic compartment." (PMID 29499041, 2018). "Expression of an array of cytokines (CSF3 [G-CSF], IFNγ, IL-1β, IL-6, IL-22, IL-17A, and IL-10), chemokines (CCL20, CXCL2 and CXCL9) and receptors (CD40) known to be involved in the regulation of S. pneumoniae inflammatory response was measured at 0, 6, 24, and 48 h post-infection." (PMID 30333823, 2018). "Unlike tight regulation to control infection spread in lymphoid organs, this local interface between IL-18-expressing and responder cell is increasingly supported in lung as disease progresses, increasing its potential to increase tissue damage via IFNγ." (PMID 28830544, 2017). "Therefore, IFNγ-stimulated infected astrocytes are potential sources of TNF, which may facilitate astrocyte infection." (PMID 28877735, 2017). "Furthermore, the compensated ganglionic CD8+ T cell populations induced by HSV-1 S1L or L8A infection failed to produce IFNγ when stimulated with fibroblasts pulsed with any of the 3 peptides." (PMID 29206240, 2017). "The interferon-gamma (IFN-γ) release assay (IGRA) is a highly sensitive and specific method for detecting Mtb infection, but it cannot distinguish latent from active infections efficiently, despite it has been commonly used for the screening and clinical diagnosis of these two stages, respectively." (PMID 28752079, 2017). "As seen for CD8+ T cells the absolute cell counts of CD4+ T cells did not increase during the course of infection but the frequency of CD4+ T cells that expressed intracellular IFNγ was significantly increased on day 7 post infection (8.54±0.60% compared to 5.66±0.27% in control mice (day 0))." (PMID 28222146, 2017). "IFNB was not induced in PBECs during co-culture and neither IFNγ nor IFNλ could be detected by ELISA in culture supernatants of THP-1 cells 24h after Mtb-infection." (PMID 28863187, 2017). "The decreased number of IFNγ+ γδ T cells in Ccr2-/- mice was not due to a defect in the total number of γδ T cells, as Ccr2-/- and B6 mice had equivalent numbers of lung γδ T cells during infection." (PMID 28384349, 2017). "Moreover, CB17 SCID mice infected with this pathogen and substituted with either CD8+ from BALB/c IFNγ−/− or BALB/c Perforin−/− mice survived the infection without showing symptoms of disease at any point in time." (PMID 28770333, 2017). "The absence of IFNγ induction in IL-33 KO mice could be explained partially by the reduction of these cells in IL-33 KO mice during early infection at 48 h PI and reconstitution of NK or NKT cells at 72 h of PI." (PMID 28607531, 2017). "Thus, mice lacking IFNγ, IFNGR1, or critical signaling components such as STAT1 are exquisitely susceptible to infections by Mycobacteria tuberculous, Listeria monocytogenes and other pathogens." (PMID 28542482, 2017). "However, despite expansion of CD4+ T cells and increased IFNγ expression in the spleen, humans with active VL do not control the infection." (PMID 28103263, 2017).
infection (continued). "However, we found that while non-gB498-505 CD8+ T cells in an S1L infection also dropped as latency was established, over 4x more non-gB-CD8s responded to infected target cells by producing IFNγ in this assay." (PMID 29206240, 2017). "No significant trends were observed in IL-6, MCP1 or IFNγ at day 12 post-infection." (PMID 28270815, 2017). "The lack of differences in IFNγ observed in our experiments may reflect the relatively late time points post-infection at which we measured the cytokine response." (PMID 27716391, 2016). "Neither vaccination nor infection with wild-type E. chaffeensis induced a significant CD8+ T cell response as measured by proliferation assay or by intracellular cytokine staining for IFNγ." (PMID 26841025, 2016). "However, the numbers of IFNγ+ and CD107a+ cNK cells only increased after infection with non-replicating cps 1-1 parasites, but not after infection with replicating RH and ME49 parasites." (PMID 27721814, 2016). "The fact that FTY720 enhanced the frequency of cells producing both TNFα and IFNγ, in MAITs, CD8 T cells, and CD4 T cells, while declining that of TNFα single-producer cells in CD4 T cells suggested beneficial effects of FTY720 on the host defense against infection." (PMID 27536542, 2016). "Hepcidin and cathelicidin was, however, not affected by IFNγ or by infection." (PMID 27324690, 2016). "If CMI is required for immunological defense against M. ulcerans infections, IFNγ which is produced primarily by TH1, but also by TC and NK cells, is likely to play a critical role in this process by activating macrophages to kill intracellular bacteria at an early stage of infection." (PMID 26863011, 2016). "However, this enhanced capacity to produce IFNγ is independent of NK cell proliferation in vitro, an event distinct from short-term arming/priming during infection." (PMID 27816971, 2016). "Moreover, STAT1β-P/STAT1β ratios declined during infection in CD46+/IFNγ-KO explants, but not CD46+ explants." (PMID 27178303, 2016). "Infection with La or Lb induced an increase in CD4+ T-cells in DLN; however, the number of CD4+ T-cells was greater in the Lb infection and displayed a Th1 immune phenotype, since IFNγ-producing CD4+ T-cells were only observed in the infection with Lb and not during La infection." (PMID 27073297, 2016). "We investigated whether a lack of IFNγ might impact the proportion of NSPCs or cells specified to the neuronal lineage during the course of infection." (PMID 27178303, 2016). "For example, IFNγ levels in the skin increased in rainbow trout upon infection with Gyrodactylus salaris although in this case other T related genes such as CD4 or CD8 were not significantly modulated by the infection." (PMID 26808410, 2016). "Furthermore, we found that the bacterial load in the mice lacking IFNγ was significantly (3.5 fold) higher after 5 weeks of infection than in WT mice, correlating with the strong foot pad swelling observed at this time point in only the mutant mice." (PMID 26863011, 2016). "In addition to this phenotype an early increase of IFNγ and an overall lower IL-17 production was observed in the absence of IL-22 during PbA infection." (PMID 27311945, 2016). "As IFNγ-mediated induction of immunoproteasome is indispensable for efficient antigen presentation of viral proteins during infection, we investigated the kinetics of immunoproteasome expression and activity in the lung after murine gammaherpesvirus-68 (MHV-68) infection in vivo." (PMID 25989070, 2015). "All IFNγ-treated mice, regardless of time of treatment, had significantly less morbidity and mortality than untreated, infected mice, with treatment as late as 24 hours following infection protecting 100% of the mice from death." (PMID 26562011, 2015).
infection (continued). "We therefore examined gene expression for several important interferon-related genes (IFNα2, IFNα4, IFNβ, IFNαβR, IFNγ, IFNγR, Irf3, Irf7, Mx1, Oas1, IFITM1, IFITM2), along with inflammasome-related genes IL-1β and NLRP3, and chemokines CCL5, CCL7, and CCL12 at d1 post-infection." (PMID 26110868, 2015). "Likewise, mice genetically deficient in CD4+ or CD8+ T cell function were extremely susceptible to infection, and it was shown that T lymphocytes act by producing type 1 cytokines, such as IFNγ, and CD8+ T cell cytotoxicity mediated by perforin is important for resistance against infection." (PMID 25951312, 2015). "However, as IFNγ was not expressed by isolated macrophages in response to infection we focused on the role of type I IFNs in PDL1 expression in isolated cells." (PMID 25775126, 2015). "Unlike IFNγ, LTα was not required for brain microvessel cross-presentation during infection." (PMID 26046849, 2015). "Our results suggest the operation of a neuroimmune signaling between peripheral immune cells and glia mediated by IFNγ which may have a role in controlling JCV gene expression and progression of the lytic infection cycle by suppressing the major viral regulatory protein, T-antigen." (PMID 26061652, 2015). "However, in a previous phase III study in burn patients, IFNγ had failed to protect patients from infection or decrease mortality." (PMID 24886820, 2014). "Tregs have been reported to modify blood-stage infection in vivo in humans including higher parasite growth rates and elevated production of transforming growth factor-beta (TGF- β) and IL-10 that lead to down-modulation of inflammatory responses mediated through interferon-gamma (IFN-γ)." (PMID 24642188, 2014). "Indeed, several B6 miR-146a−/− mice did have elevated serum IFNγ at 4 weeks post-infection, although this was the exception rather than the rule, and average levels did not achieve statistical significance compared to wild-type mice." (PMID 24967703, 2014). "In contrast, these bands could not be detected in E. cuniculi-infected IFNγ-induced cells either 2 or 5 days after infection." (PMID 25356593, 2014). "To assess the role of STAT1 transcription factor in IFNγ-dependent protection against infection by T. cruzi, we first performed invasion assays using trypomastigotes in HFF cells expressing endogenous STAT1 and in STAT1-negative U3A cells, both in the absence and presence of IFNγ." (PMID 25340519, 2014). "Interestingly, in the absence of exogenous αGalCer treatment, there is little evidence that IFNγ production by iNKT cells is protective during infection." (PMID 24391492, 2014). "Mice fed once or twice with live P. marinus and examined at day 6 post-feeding, as well as control unfed mice, had undetectable levels of IFNγ in serum as measured by luminex (<1 pg/ml), which indicated that P. marinus did not induce infection or noticeable adverse events." (PMID 24498105, 2014). "Specifically, one infection was characterized by morphologically normal late-stage inclusions, high viable bacterial numbers, and a low euo:omcB mRNA expression profile, together with the presence of a high concentration of indole and no IFNγ." (PMID 24918090, 2014). "The number of meronts observed in Irgm1/Irgm3−/− MEF cells 24 h after infection was the same whether the cells were induced with IFNγ or not." (PMID 25356593, 2014). "Moreover, we found that infection of HFF cells and A549 cells with the parasite leads to phosphorylation of the critical tyrosine 701 and serine 727 residue, both of which are required for maximal transcriptional response to IFNγ." (PMID 25340519, 2014). "Thus the factors that limited the accumulation of IFNγ-producers at the infection site had not been identified." (PMID 23991011, 2013). "However, they found the levels of IFNγ between pDC depleted and control mice at the later stage of infection was not different." (PMID 24386207, 2013).
infection (continued). "However, commercial interferon gamma (IFN-γ) release assays (IGRAs: T-SPOT®.TB and QuantiFERON®; Qiagen Inc., Valencia, California, USA), cannot discern TB from latent TB infection (LTBI), two infection phenotypes that differ significantly in bacterial burden." (PMID 24324704, 2013). "Following infection by C. parvum sporozoites in vitro, the mouse epithelial cell line CMT-93 upregulated CXCL9 and CXCL10 24 h later suggesting that independently of IFNγ, IEC can in some conditions upregulate these chemokines in direct response to the parasite." (PMID 24367259, 2013). "Of the 14 Th1 response genes tested, the expression levels of 8 genes (IL2, IFNG, CSF2, TLR4, CD4, IRF1, SOCS5 and STAT4) were significantly elevated at 2 weeks and several of these (IL2, IFNG, TLR4, CD4 and STAT4) had similar expression levels at 4 and 8 weeks post-infection." (PMID 23448601, 2013). "Since the cytokine levels were elevated before the T cell response was initiated, these data suggest that antigen-specific CD4 T cells may not be the primary source of serum IFNγ during infection." (PMID 23754944, 2013). "Irf8-deficient mice, then, display defective Th1 responses (absence of antigen specific and IFNγ producing CD4+ T cells), enhanced Th17 responses, and are susceptible to in vivo infection with many intracellular pathogens including tuberculosis and blood-stage malaria." (PMID 23853600, 2013). "For a long time it was not clear how astrocytes combat the infection against T. gondii, given the fact that the common IFNγ-induced mechanisms used by classical phagocytotic cells such as macrophages and microglia as NO-and IDO-mediated tryptophan degradation are not detectable in astrocytes." (PMID 24324375, 2013). "This class includes IFNγ that is synthesized by infected cells in the absence of other cell types, and several types of IFNα that are synthesized primarily by leukocytes recruited to the infection site." (PMID 23383295, 2013). "However, little or no IFNγ or IL-12p70 was detectable at any time during the S. Typhimurium SL1344(p1C/1) infection of the ESC derived DCs." (PMID 23284947, 2012). "We next determined IRF1 levels after infection in the absence of IFNγ." (PMID 23240025, 2012). "The functional heterogeneity of AM is driven primarily by pathogens and environmental IFNγ and IL-4 ratios; disruption of influences that control the CAM and AAM balance could have severe consequences on airway inflammation and resolution of infection." (PMID 22792355, 2012). "Depletion of CD11c+ cells from day 21 to day 28 of infection did not affect the frequency of antigen-specific IFNγ+ T cells (35.78±4.18% vs. 30.33±5.32% after saline or DTx, respectively), although absolute numbers were decreased by approximately 2-fold in keeping with the reduction of spleen size." (PMID 22911108, 2012). "However, the absence of differences in serum levels of IL-4, IL-12, IFNγ and GM-CSF after infection does not exclude the possibility that they are involved in the local response to L. tropica." (PMID 22679519, 2012). "In support of this hypothesis, our preliminary data suggest that ISG expression is altered by RIG-I downstream of IFNγ during infection (data not shown)." (PMID 22912573, 2012). "Thus, the absence of TLR2 and 4 reduces IFNγ release in the lymph nodes and lungs and lymph node T-cell proliferation that correlate with increased severity of Chlamydia respiratory disease and infection in early life." (PMID 22724018, 2012). "In addition, N1N2ΔCD4Cre mice do not control infection revealing that N3 and N4 are not functionally redundant in driving IFNγ secretion by CD4+ T cells." (PMID 22396647, 2012). "The results showed that (i) growth of KOS and JD0G was inhibited by IFNγ at low MOI on both cell lines; (ii) JD0G was somewhat more sensitive than KOS; (iii) both viruses at low MOI were hypersensitive to IFNγ on U251 cells; and (iv) high-MOI infection minimized IFNγ sensitivity." (PMID 22924042, 2012).